ABO (ABO, alpha 1-3-N-acetylgalactosaminyltransferase and alpha 1-3-galactosyltransferase)
Diseases named in the same sentence as ABO in open-access papers (continued):
Sharing a sentence is not in itself a finding about the gene and the disease.
malaria (continued). "Some genetic variations, such as those found in the hemoglobin subunit beta (HBB), ABO blood group (ABO), ATPase plasma membrane Ca2+ transporting 4 (ATP2B4), glucose-6-phosphate dehydrogenase (G6PD) and CD40 ligand (CD40LG) loci, have been associated with attenuation of severe malaria." (PMID 36895563, 2023). "Whether the non-O blood groups encoded by the specific ABO genotypes AO, BO, AA, BB and AB differ in their associations with severe malaria and rosetting is unknown." (PMID 37708213, 2023). "However, the concordance between ABO genotype and ABO phenotype has not been reported in previous population studies of malaria susceptibility, most of which have been conducted in sub-Saharan Africa." (PMID 37708213, 2023). "Finally, blood‐type molecular and genotyping studies on malaria patients with weak A alleles in connection with nonimmune, natural anti‐A/Tn levels potentially provide even more insight into the actual trend of ABO(H) blood group evolution." (PMID 29754430, 2018). "The hypotheses on why blood group O protects from malaria, and from severe malaria in particular, include aspects of differential attractiveness to Anopheles vectors, shared ABO antigens with P. falciparum, impaired merozoite penetration as well as reduced cyto-adherence." (PMID 25066505, 2014). "Thus, malaria selection may be a plausible explanation for the shift in ABO distributions that we observed within a single nation and generation." (PMID 22909232, 2012). "Some of the genes that confer resistance to malaria are among the most variable genes in the human genome, as seen in the human leukocyte antigen (HLA), G6PD, globin, and ABO genes." (PMID 40709108, 2025). "We focus on a curated set of systems, ABO, Duffy, MNS, Gerbich, Knops, Diego, and others, and outline their molecular mechanisms affecting malaria." (PMID 41450567, 2025). "There are extensive reports in the literature regarding selection pressure driven by malaria in the HBB, ABO, DARC and G6PD genes." (PMID 30849090, 2019). "The case of the O allele at the ABO locus may be an example of within-locus balancing selection: whereas the O allele clearly protects against malaria, non-O alleles may protect against other diseases caused by viruses and bacteria which show strong comorbidity with malaria." (PMID 26744416, 2016). "The ten most commonly offered tests in decreasing order were Malaria, HCG, HIV serology, Syphilis, Typhoid, Urinalysis, Brucellosis, Stool Analysis, Glucose, and ABO/Rh." (PMID 26226183, 2015). "Nevertheless, alleles of different well-known genes that are likely to have undergone selection by malaria have been identified using this approach, such as GYPC (glycophorin C), ABO (ABO blood group), and SLC4A1 (erythrocyte membrane protein band)." (PMID 24005574, 2014). "Parasite density in the severe malaria cases did not vary significantly across the different ABO genotypes." (PMID 37708213, 2023). "Moreover, the acquisition of relative immunity with age greatly confounds the influence of ABO blood group, G6PD and haemoglobin genotype on malaria." (PMID 32646433, 2020). "None of the ABO bloodgroups showed any significant influence on malaria incidence rates in this cohort." (PMID 28793894, 2017). "This study suggests that the protective effect of the sickle cell trait may be linked to the raised level of Transforming Growth Factor beta and provides additional support for a role of ABO and RTN3 against severe malaria." (PMID 24934404, 2014). "This study suggests that the protective effect of the sickle cell trait may be linked to the raised level of TGF-ß and provides additional support for a role of ABO and RTN3 against severe malaria." (PMID 24934404, 2014).
malaria (continued). "This increased the strength of the evidence that HBB, ABO, HBA1-2, and FREM3/GYP are associated with protection against severe malaria compared with the non-weighted case–controls odds-ratios (for HBA1-2: p = 10−5 versus p = 10−4; ABO: p = 10−13 versus p = 10−8; FREM3: p = 10−12 versus p = 10−11)." (PMID 35676275, 2022). "Whether the absence of immunodominant sugars is more permissive to malaria-induced band 3 aggregation is unknown, as ABO effects have not previously been specified in such studies." (PMID 23071435, 2012). "Thus, this study investigated the hypothesis that ABO blood groups are associated with the severity of P. falciparum infection and the results showed that non-O blood group children are more prone to severe malaria caused by P. falciparum than the group O children." (PMID 22187584, 2011).
pancreatic cancer (44 papers, 2011 to 2025). "Few comprehensive studies have examined the associations of the ABO blood group with survival outcomes for patients with resected pancreatic cancer, overall and by adjuvant chemotherapy regimens." (PMID 40314902, 2025). "A key finding connecting ABO, pancreatic cancer risk and VTE is data showing that two ABO SNPs (rs505922 and rs657152) are associated with both PDAC and cardiocerebrovascular diseases." (PMID 39002386, 2024). "CTRB1 and ABO were associated with risk of pancreatic cancer of which one was only associated with pancreas cancer and largely only expressed in the exocrine pancreas, CTRB1 [OR: 0.79, 95% CI: 0.73 to 0.85; PP4: 0.99]." (PMID 38684708, 2024). "Since ABO is linked with diseases that are related to pancreatic carcinoma and other genes are related to these diseases as well, HOGCN captures such association even though they are farther away in the network." (PMID 33587705, 2022). "The Pancreatic Cancer Cohort Consortium (PanScan) reported that the most significant variants associated with pancreatic cancer risk were mapped to the ABO locus." (PMID 34202464, 2021). "Results from a GWAS on pancreatic cancer risk showed that the more common T allele, which is in LD with a base pair deletion coding for the O-antigen in ABO, had a protective association with pancreatic cancer." (PMID 34777790, 2021). "Data from PanScan demonstrated that, among all common ABO variants, the greatest risk of pancreatic cancer was conferred by the A1 allele 13 which gives rise to the ABO protein with highest enzymatic activity." (PMID 28556564, 2017). "Given that ABO blood types are inherited through genes on chromosome 9q34, a genome-wide association study also noted an association between DNA sequence variants in the ABO locus and susceptibility to pancreatic cancer." (PMID 28880901, 2017). "The Multinational Pancreatic Cancer Consortium successfully identified susceptibility loci in the ABO gene for pancreatic cancer pathogenesis." (PMID 29246245, 2017). "For example, the multinational Pancreatic Cancer Cohort Consortium identified pancreatic cancer susceptibility loci in the ABO gene." (PMID 27733208, 2016). "In 2009, an agnostic approach to identify genes associated with risk of developing pancreatic cancer further supported the association between the ABO blood group and cancer." (PMID 28031957, 2016). "Two other studies suggested that the association between A blood group and increased risk of pancreatic cancer is due mainly to the A1 allele, thus indicating a direct connection between ABO glycosyltransferase activity and increased risk of this disease." (PMID 27733208, 2016). "Genotyping of 558,542 SNPs in 1896 patients with pancreatic cancer and 1939 controls revealed a significant association between SNP rs505922, located within the first intron of ABO." (PMID 28031957, 2016). "The other three of these SNPs showed a decreased risk of melanoma: two TERT/CLPTM1L SNPs previously associated with lung cancer (rs402710, OR = 0.87; rs31489, OR = 0.89) and one ABO SNP previously associated with pancreatic cancer (rs505922, OR = 0.89)." (PMID 25789475, 2015). "A genome-wide association study (GWAS) of pancreatic cancer identified a genetic variation in the ABO locus of 9q34 that was associated with susceptibility to pancreatic cancer." (PMID 26411553, 2015). "The positive association between the ABO blood types and survival has been suggested in several malignancies, including pancreatic cancer, breast cancer, renal cell carcinoma, nasopharyngeal carcinoma, and colon cancer." (PMID 26411553, 2015). "Intriguingly, a robust association of the ABO histo-blood group with pancreatic cancer reported in earlier epidemiological studies has been established using a modern genome-wide association study." (PMID 24586218, 2014).
pancreatic cancer (continued). "Our results are compatible with the previously reported association between the ABO gene and pancreatic cancer, and show that the effect of these common variants at the ABO locus on the P-LIP and ACE levels is largely opposing and pleiotropic." (PMID 24586218, 2014). "Recently, several epidemiological observations have found a relationship between ABO blood group genotypes and pancreatic cancer risk." (PMID 22911869, 2012). "The mechanism by which blood group affects cancer risk is unknown, although it is hypothesized that ABO antibodies interact with aberrant glycoproteins expressed on pancreatic tumour cells." (PMID 38124529, 2024). "Research from 2009 identified 558,542 gene regions that may be potentially associated with the risk of developing pancreatic cancer, SNP rs 505922 located within the first intron of the ABO gene." (PMID 39040623, 2024). "Moreover, the ABO blood group has been associated with pancreatic cancer, nasopharyngeal carcinoma, and ovarian and lung cancers." (PMID 36350001, 2022). "In addition, a large prospective cohort study found that increased glycosyltransferase activity corresponding to the ABO allele subtype was associated with an increased risk of pancreatic cancer." (PMID 36464709, 2022). "Our study suggested that ABO polymorphisms might serve as a risk factor of pancreatic cancers and cardiocerebrovascular diseases." (PMID 32093636, 2020). "Notably, we confirmed the significant association (P = 3.84 × 10−5) between rs505922 of the ABO locus and pancreatic cancer risk." (PMID 32581250, 2020). "Our study demonstrates that pancreatic cancer risk is influenced by ABO status, in particular blood groups O and A1, and that this association may reflect also in tumor resectability and survival." (PMID 28556564, 2017). "Here, we have investigated ABO genetic variants and phenotypes in the context of pancreatic cancer." (PMID 28556564, 2017). "Interestingly, a recent meta-analysis provided some evidence that ABO rs505922 SNP C allele is a risk factor for cancer susceptibility, specifically for pancreatic cancer." (PMID 27999448, 2016). "How this SNP contributes to increased risk of pancreatic cancer and whether this SNP or any other variants of the ABO blood group system are associated with other types of cancers remains unclear." (PMID 28031957, 2016). "In addition, two recent genome-wide association studies identified variants in ABO (rs505922), 1q32.1 (rs3790844), 13q22.1 (rs9543325), and 5p15.3 (rs401681) that were associated with a modestly increased risk of pancreatic cancer." (PMID 27733208, 2016). "In this study, 1896 patients with pancreatic cancer and 1939 controls were genotyped, and a significant association was reported with rs505922, a single nucleotide polymorphism (SNP) that maps to the first intron of the ABO gene." (PMID 27733208, 2016). "Examples include the association of the APOE/TOMM40 locus with pancreatic cancer and total cholesterol levels, the association of the ABO locus with macular degeneration and coronary artery disease, and the association of the SH2B3/ATXN2 locus with diastolic blood pressure and rheumatoid arthritis." (PMID 26677855, 2015). "Current evidence found that human ABO blood groups or genetic variations on ABO gene were associated with the risk of various diseases, such as pancreatic cancer, gastric cancer, falciparum malaria, venous thromboembolism, myocardial infarction and type 2 diabetes." (PMID 24094242, 2013). "It is noteworthy that 2 recent genome-wide association studies of pancreatic cancer have reported that variants in ABO blood type and in 3 other chromosomal regions are associated with risk for this cancer, thus providing new insight into pancreatic cancer etiology." (PMID 21071884, 2011).
pancreatic cancer (continued). "In addition, two recently completed genome-wide association studies (GWAS), PanScan1 and PanScan2, have identified variants in ABO (rs505922), 1q32.1 (rs3790844), 13q22.1 (rs9543325) and 5p15.3 (rs401681) that are associated with a modestly increased risks of pancreatic cancer." (PMID 24058443, 2013). "We found another similar study conducted on the ABO blood group and different cancers including gastric cancer, esophageal cancer, breast cancer, ovarian cancer, nasopharyngeal cancer, and pancreatic cancer." (PMID 38167167, 2024). "In order to further explore a potential function for ABO glycosyltransferase and ABO antigen expression in pancreatic cancer etiology, researchers have looked at variations in the ABO and FUT2 genes." (PMID 38167167, 2024). "There are many studies regarding ABO blood group and rhesus factor which reported different impact on different types of cancers such as breast cancer and pancreatic cancer." (PMID 36181128, 2022). "Specifically, we choose gene-disease pairs (a) ABO and Pancreatic carcinoma (26 pieces of evidence) and (b) GPC3 and Hepatoblastoma ((17 pieces of evidence)." (PMID 33587705, 2022). "In particular, there are 49 shortest paths of length 3 between ABO and Pancreatic carcinoma including 6 diseases and 15 genes." (PMID 33587705, 2022). "We therefore collected information on ABO blood group distribution from a large control cohort of unselected hospitalized patients from the same geographical region as our pancreatic cancer patients." (PMID 28556564, 2017). "Blood type has been linked to multiple diseases, and genome-wide association studies (GWAS) have found associations between ABO variants and susceptibility to coronary artery disease (CAD), venous thromboembolism (VTE), and pancreatic cancer." (PMID 28448592, 2017). "Among these studies, the relationship between the ABO blood group and the incidence of gastric and/or pancreatic cancer is considered to be reliable and convincing, as the studies were large-scale meta-analyses." (PMID 25483106, 2015). "Recent genome-wide association studies (GWAS) and post-GWAS analyses have identified chromosome regions containing the ABO, NR5A2, and CLPTM1L-TERT genes, as well as the HNF1A gene, as susceptibility loci for pancreatic cancer." (PMID 23056513, 2012). "Common low penetrance variants in gene loci including ABO, TERT and PDX1 that contribute to pancreatic cancer risk have been identified through genome-wide association studies, but much of the familial clustering of pancreatic cancer remains unexplained." (PMID 28881607, 2017). "In 2009, a link between the ABO blood group and risk of pancreatic cancer was established, not by evaluating blood groups, but through a genome-wide association study (GWAS) linking an SNP in the first intron of ABO with increased risk." (PMID 28031957, 2016). "Several single nucleotide polymorphisms (SNPs) in the gene regions of ABO, sonic hedgehog (SHH), telomerase reverse transcriptase (TERT), nuclear receptor subfamily 5, group A, member 2 (NR5A2) were found to be associated with pancreatic cancer risk." (PMID 22125638, 2011). "Single nucleotide polymorphisms (SNPs) in ABO, sonic hedgehog (SHH), telomerase reverse transcriptase (TERT), nuclear receptor subfamily 5, group A, member 2 (NR5A2) were found to be associated with pancreatic cancer risk." (PMID 22125638, 2011). "However, the biology behind the fascinating ABO‐pancreatic cancer link is poorly understood, and studies are warranted on how ABO glycosyltransferase activity may influence biological aggressiveness of pancreatic neoplastic cells." (PMID 28556564, 2017). "The ABO SNP rs505922 is in strong linkage disequilibrium with O/non-O blood group alleles, indicating that people with non-O blood groups are at increased risk for developing pancreatic cancer." (PMID 27733208, 2016).
pancreatic cancer (continued). "In addition, all four genetic variants tested were associated with pancreatic cancer (OR for non-O ABO genotypes ranged from 1.25 to 1.58, and the per-allele odds ratios for the other three risk SNPs ranged from 1.18 to 1.49)." (PMID 24058443, 2013). "The ABO single nucleotide polymorphism (SNP) rs505922 is in strong linkage disequilibrium with O/non-O blood group alleles indicating that individuals with non-O blood groups are at an increased risk of developing pancreatic cancer." (PMID 24058443, 2013). "Serology‐based analyses and many genetic studies of ABO blood groups in pancreatic cancer do not distinguish between A1 and A2 subgroups." (PMID 28556564, 2017). "The ABO blood group is not a prognostic biomarker in resected pancreatic cancer overall but may predict the effectiveness of adjuvant chemotherapy." (PMID 40314902, 2025).